CTLA4 (cytotoxic T-lymphocyte associated protein 4)
Diseases named in the same sentence as CTLA4 in open-access papers (continued):
Sharing a sentence is not in itself a finding about the gene and the disease.
cancer (continued). "Immunoinhibitory checkpoint pathways (cytotoxic T lymphocyte-associated protein-4 [CTLA-4]/B7, programmed cell death-1 [PD-1]/programmed cell death ligand-1 [PD-L1]) are emerging as interesting immunotherapeutic targets for the treatment of cancer." (PMID 25935754, 2015). "Considering the fact that most common SNPs usually make low penetrance cancer susceptibility, this study includes 13 case-control studies with relatively large sample sizes to obtain a precise evaluation between CTLA-4 -1722T/C genetic variation and cancer risk." (PMID 24710335, 2014). "With a growing interest in the associations of genetic polymorphisms and cancer, several studies have examined the hypothesis that CTLA-4 -1722T/C polymorphism is relevant to the risk of a number of cancers; however, the results remain elusive." (PMID 24710335, 2014). "It has been hypothesized that during the early stage of tumorigenesis, CTLA-4 may elevate the T-cell activation threshold, thereby attenuating the antitumor response and increasing cancer susceptibility." (PMID 23936819, 2013). "Meta-analysis of the CTLA-4 -1661A/G (rs4553808) polymorphism and cancer risk." (PMID 24376736, 2013). "However, most of the studies are based on peripheral blood mononuclear cells, and much less is known about the relationship between CTLA-4 expression, especially gene expression, and its polymorphic variants in cancer tissue." (PMID 23936819, 2013). "Thus, the association between CTLA-4 gene polymorphisms and cancer susceptibility requires further investigation." (PMID 24376736, 2013). "Hence, in this paper, we perform a meta-analysis on previous reports to investigate the association of CTLA-4 gene polymorphism with cancer." (PMID 24376736, 2013). "It has been suggested that during early stages of tumorigenesis, CTLA-4 may elevate the T-cell activation threshold, attenuating the antitumor response and increasing cancer susceptibility." (PMID 24376736, 2013). "However, studies focusing on the association of the CTLA-4 gene polymorphism with cancer susceptibility had controversial conclusions." (PMID 24376736, 2013). "Meta-analysis of the CTLA-4 60G/A (rs3087243) polymorphism and cancer risk." (PMID 24376736, 2013). "Our meta-analysis suggests that the CTLA-4 +49G > A polymorphism genotypes (GA + AA) might be associated with an increased risk of cancer, especially in Caucasians and Chinese." (PMID 20920330, 2010). "This indicates that biases from publications and other factors may not have had a significant influence on the results of our meta-analysis on the association between CTLA-4 +49G > A polymorphism and cancer risk." (PMID 20920330, 2010). "It was also demonstrated that the increased risk of cancer associated with CTLA-4 +49G > A variant genotypes was more pronounced in Caucasians (OR = 1.29, 95% CI = 1.13-1.47, P = 0.0002), Asians (OR = 1.23, 95% CI = 1.16-1.32, P < 0.00001) and Chinese (OR = 1.23, 95% CI = 1.15-1.31, P < 0.00001)." (PMID 20920330, 2010). "The combination of direct enhancement of CTL function and concomitant inhibition of Treg function through blockade of cytotoxic T lymphocyte-associated antigen 4 (CTLA-4) on both cell types is essential for mediating the full therapeutic effects of anti-CTLA-4 antibodies in cancer immunotherapy." (PMID 20182533, 2009). "Cancer immunotherapy, particularly immune checkpoint inhibitors (ICIs) that target programmed cell death protein 1 (PD-1), programmed death-ligand 1 (PD-L1), and cytotoxic T-lymphocyte-associated antigen 4 (CTLA-4), has significantly advanced the field of oncology." (PMID 42125897, 2026). "Immunotherapy has revolutionized cancer treatment, particularly with the advent of immune checkpoint inhibitors (ICIs) that target programmed cell death protein 1 (PD-1), programmed death-ligand 1 (PD-L1), and cytotoxic T-lymphocyte-associated protein 4 (CTLA-4)." (PMID 40567374, 2025).
cancer (continued). "Additionally, ORAOV1 expression correlated with enhanced infiltration of immunosuppressive cells, including regulatory T cells, myeloid-derived suppressor cells, and cancer-associated fibroblasts, as well as upregulation of immune checkpoint markers (PD-1, PD-L1, and CTLA-4)." (PMID 41321947, 2025). "Similarly, immunotherapies like pembrolizumab and nivolumab, which target programmed death-1 (PD-1) and cytotoxic T-lymphocyte-associated protein 4 (CTLA-4) pathways, have shown promise in attacking cancer cells by unleashing the immune system, but their effectiveness varies among patients." (PMID 41364140, 2025). "Our data support this hypothesis in that the increase in autoreactive B cells following combined CTLA-4 and PD-1 blockade in patients with cancer was associated with elevated proportions of blood Tregs with decreased RGS1 expression, which favors T cell egress from the gut." (PMID 41026527, 2025). "Furthermore, cancer cells hijack the immune checkpoint pathway, such as programmed cell death protein 1 (PD-1) and cytotoxic T-lymphocyte-associated protein 4 (CTLA-4), which are essential for maintaining immune homeostasis and preventing excessive immune responses." (PMID 39810853, 2025). "Our results have indeed confirmed that tumors with higher RiskScore are more likely to benefit from anti-CTLA-4 (cytotoxic T-lymphocyte-associated protein 4) therapy, which is a type of immunotherapy that targets immune checkpoints to enhance the activity of T cells against cancer cells." (PMID 39044041, 2024). "CTLA-4 is a critical immune checkpoint, and it has been suggested that a variant of variable-number tandem repeat in the 3’-UTR of its gene, known as (AT)n, may be associated with a higher susceptibility to some cancers; however, little is known about genetic variants of the CTLA-4 gene in NMSC." (PMID 39194710, 2024). "The immune checkpoint proteins PD-1 and cytotoxic T-lymphocyte-associated protein 4 (CTLA-4) have been shown to act as brakes on the immune function, suggesting that immune checkpoint inhibition can reactivate T cells and more effectively eliminate cancer cells." (PMID 39407830, 2024). "Immune Checkpoint Inhibitors (ICIs), a new generation of anti-cancer drugs, liberate the immune system enabling it to destroy tumorous growths by inhibiting negative costimulatory molecules like cytotoxic T lymphocyte-associated protein-4 (CTLA-4) and programmed death receptors (PD-1/PD-L1)." (PMID 38357311, 2024). "There are several types of cancer immunotherapies that target specific antibodies: There are antibodies targeting programmed cell death protein-1 (PD-1), programmed cell death ligand (PD-L1), and cytotoxic T-lymphocyte associated protein 4 (CTLA-4) checkpoints." (PMID 38406102, 2024). "In recent years, the anti-cytotoxic T-lymphocyte-associated protein 4 (anti-CTLA-4) and against programmed cell death receptor 1 (PD-1) and its ligand (PD-L1) have gradually become the focus of research and development and have fully proven their potential as “cancer killers”." (PMID 38361920, 2024). "However, cancers often evade immune detection through immune checkpoints, such as the cytotoxic T lymphocyte-associated protein 4 (CTLA-4), the programmed cell death protein-1 (PD-1), and the programmed cell death ligand-1 (PD-L1), which inhibit the physiological activation of T cells." (PMID 38675461, 2024). "The Cytotoxic T-Lymphocyte Associated Protein-4 (CTLA4) and programmed cell death-1 (PD-1) checkpoint pathways are inhibitory pathways, and blocking these inhibitory pathways with mAbs has triggered antitumor immune responses that altered the cancer therapy field." (PMID 38234663, 2024). "Monoclonal antibodies targeting cytotoxic T-lymphocyte-associated protein 4 (CTLA-4) or programmed cell death protein 1 (PD-1) or its associated programmed cell death ligand 1 (PD-L1) have since been approved as monotherapies or in combination with existing treatments for various cancer types." (PMID 38256021, 2024).
cancer (continued). "The treatment efficacy of malignant tumors has been greatly improved by the introduction of immune checkpoint inhibitors (ICIs), including programmed cell death protein-1 (PD-1)/programmed cell death-ligand 1 (PD-L1) and cytotoxic T-lymphocyte-associated protein 4 (CTLA-4) monoclonal antibodies." (PMID 38850335, 2024). "In a considerably larger validation cohort (“tmb_mskcc_2018”) comprising 1661 pan-cancer patients, 8 out of the top 20 ranked gene mutations from the discovery cohort were detected in patients who all underwent PD-1 or cytotoxic T lymphocyte antigen 4 (CTLA-4) blockade treatment (upper)." (PMID 38951894, 2024). "Two meta-analyses found similar results regarding the rs231775 variant, showing an associated risk for cancer development even through subgroup analysis by type and ethnicity suggesting that CTLA-4 rs231775 is a key variant that could be associated with cancer development." (PMID 37107632, 2023). "Notably, ICIs, which target immunosuppressive pathways like PD-1 (programmed cell death protein 1), PD-L1 (programmed cell death ligand 1), and CTLA-4 (cytotoxic T-lymphocyte-associated protein 4), have shown promising results in combination with personalized cancer vaccines." (PMID 37895855, 2023). "Data suggest that microbiota adjustment may present a novel strategy for improving the efficacy of immunotherapies for cancer, particularly checkpoint blockade approaches targeting the cytotoxic T-lymphocyte-associated protein 4 and programmed cell death ligand-1 (PD-L1) pathways." (PMID 38179448, 2023). "As a proof of concept of this strategy, we generated an Adenovirus vector encoding a murine anti-CTLA-4 monoclonal antibody (Ad-9D9), and tested its adjuvant effect on adaptive immune responses when co-administered in a mixture with Adenoviral-based vaccines encoding for viral or cancer antigens." (PMID 37180141, 2023). "Therefore, CTLA4 inhibition would cause the activation of Tc cells against cancer cells." (PMID 36902456, 2023). "In this context, the discovery of immune checkpoints like cytotoxic T lymphocyte-associated antigen 4 (CTLA-4) and programmed death/ligand 1 (PD-1/PD-L1) has enabled the development of immune checkpoint inhibitors (ICIs), antibodies that target these checkpoints for the treatment of cancer." (PMID 37894280, 2023). "Cancer immunotherapies targeting immune checkpoint pathways, such as programmed cell death-1 (PD-1)/programmed cell death ligand-1 (PD-L1) and cytotoxic T-lymphocyte-associated antigen-4 (CTLA-4), have achieved unprecedented therapeutic success in treating various types of cancer." (PMID 37614504, 2023). "The CTLA-4 gene polymorphism −658C/T (rs11571317) is found in the promoter region, which induces the pattern of alternative splicing aberrantly and may alter the pattern of gene expression, leading to the predisposition of cancer progression." (PMID 38186404, 2023). "Cancer treatment includes surgery, sessions of chemotherapy, radiotherapy and nowadays, immunotherapy such as immune checkpoint blockades, including those targeting cytotoxic T lymphocyte-associated protein 4 (CTLA-4) and programmed cell death protein 1/programmed cell death ligand 1 (PD-1/PD-L1)." (PMID 36631633, 2023). "In recent years, immune checkpoint blockade (ICB) therapy has caused a paradigm shift in cancer immunotherapy; it primarily inhibits various checkpoints that control host T cell activity by regulating the immune checkpoint interactions, PD-1/PD-L1 and CTLA-4/CD80." (PMID 36142412, 2022). "Furthermore, the CTLA-4 competitive binding to B7.1 inhibits IL-2 production and proliferation, both of which are essential in down-regulating T cell activity; in turn, this reduces anti-tumor responses and increases cancer susceptibility." (PMID 35600409, 2022).
cancer (continued). "However, some cancers have developed methods to escape the immune system via increased expression of inhibitory immune checkpoints, such as programmed cell death ligands 1 and 2 (PD-L1, PD-L2) and cytotoxic T-lymphocyte-associated protein 4 (CTLA-4)." (PMID 35481923, 2022). "Major advances in cancer treatment have emerged with the introduction of immunotherapies using blocking antibodies that target T-cell inhibitory receptors, such as programmed death-1 (PD-1) and cytotoxic T-lymphocyte-associated antigen-4 (CTLA-4), known as immune checkpoints." (PMID 36654823, 2022). "Overall, we found that the CTLA-4 rs231775 polymorphism may reduce cancer risk." (PMID 35600409, 2022). "Recent cancer treatment applications of immunotherapy include chimeric antigen receptor T cells, vaccine therapy, and immune checkpoint blockers (ICBs) targeting programmed cell death-ligand 1/programmed death protein 1 (PD-L1/PD-1) and cytotoxic T lymphocyte-associated protein 4 (CTLA-4)." (PMID 36313698, 2022). "In contrast, CTLA4, which could encode a protein that transmits an inhibitory signal to T cells and its upregulation has been described as a marker of T cell exhaustion in chronic infections and cancer, has a high RP score in JUNB GRNs in terminal TEx." (PMID 36155797, 2022). "In addition to the currently used anti-PD-1/PD-L1 or anti-CTLA-4 therapeutic drugs, cancer-associated fibroblasts and tumor-associated macrophages (TAMs) in the microenvironment are also considered as potential targets for cancer treatment." (PMID 35765945, 2022). "It has been proved that monoclonal antibody blocking cytotoxic T-lymphocyte-associated antigen 4 (CTLA-4) and programmed cell death protein 1 (PD-1) immune checkpoint pathways and chimeric antigen receptor T cell therapy have achieved initial success in clinical treatment of cancer patients." (PMID 36589748, 2022). "Thus, cancer immunotherapy targeting proteins including programmed cell death-1 (PD-1) and programmed cell death ligand-1 (PD-L1), lymphocyte activation gene 3 (LAG-3), and cytotoxic T-lymphocyte-associated antigen-4 (CTLA-4), proved to be effective in different types of cancers." (PMID 34771722, 2021). "Immune checkpoint molecules, such as cytotoxic T-lymphocyte-associated protein 4, programmed cell death-1/programmed death-ligand 1, and their inhibitors, have attracted significant attention for overcoming the immunosuppressive conditions in patients with cancer." (PMID 35008367, 2021). "In the last decade, immunotherapy has emerged as the fourth pillar in cancer therapy via the targeting of immune checkpoint molecules such as programmed cell-death protein-1 (PD-1), programmed cell death ligand-1 (PD-L1), and cytotoxic T-lymphocyte-associated protein 4 (CTLA-4)." (PMID 33634137, 2021). "Recently, immune checkpoint molecules, such as cytotoxic T-lymphocyte-associated protein 4, programmed cell death-1/programmed death-ligand 1, and their inhibitors, have attracted significant attention for overcoming the immunosuppressive conditions in patients with cancer." (PMID 35008367, 2021). "This facilitates cancer cells to escape from destruction by the immune system, and could limit the therapeutic efficacy of current immunotherapies that target cytotoxic T lymphocyte-associated protein 4 (CTLA-4) or programmed death ligand 1 (PD-L1)/programmed death 1 (PD-1)." (PMID 33562495, 2021). "Immune-checkpoint inhibitors (ICIs) target these cancer proteins aiming at preventing the binding with their partners located at the plasma membrane of immune system cells, such as cytotoxic T lymphocyte-associated antigen 4 (CTLA-4), programmed cell death 1 (PD-1), and its ligand, PD-L1." (PMID 34068398, 2021). "Therefore, the gene status of CTLA-4 may be related to the occurrence of cancer which is a combination of genetic susceptibility and external factors." (PMID 33819967, 2021).
cancer (continued). "In addition, cancer immunotherapies, including programmed cell death protein 1 (PD-1)/programmed death ligand 1 (PD-L1) and cytotoxic T lymphocyte-associated antigen 4 (CTLA-4) checkpoint inhibitors, are being developed as promising alternative strategies for treating patients with advanced NSCLC." (PMID 34123822, 2021). "Polymorphism in the CTLA-4 gene may confer predisposition to cancer." (PMID 33819967, 2021). "A great number of researchers have found that immune checkpoints such as PD-1/PD-L1/PD-L2 and cytotoxic T-lymphocyte-associated antigen-4 (CTLA-4) enable cancer cells to bypass human immunosurveillance, which therefore might be promising targets for immunotherapy." (PMID 32596285, 2020). "Importantly, we found that PD-1/CTLA4 expression is associated with cancer immunity." (PMID 33072070, 2020). "In the past 10 years, there has been a huge development in cancer immunotherapies with the introduction of immune checkpoint inhibitor therapies towards programmed cell death protein 1 (PD-1), programmed death ligand-1 (PD-L1), and cytotoxic T-lymphocyte-associated antigen 4 (CTLA-4)." (PMID 31952311, 2020). "Immune checkpoint inhibitors (CPIs) that target the cytotoxic T-lymphocyte-associated antigen 4 (CTLA-4) and the programmed cell death protein-1 (PD-1)/programmed cell death ligand-1 (PD-L1) pathway have demonstrated remarkable efficacy across a wide variety of cancer types." (PMID 33520695, 2020). "A most interesting mechanism by means of which cancer cells can further promote immunosuppression is the upregulation of checkpoint inhibitor molecules like PD-L1 and cytotoxic T-lymphocyte-associated Protein 4 (CTLA4), which confer inhibitory signals to the immune cells." (PMID 31295960, 2019). "Indeed, therapies targeting immune-checkpoint molecules (e.g., programmed cell death 1 (PD-1), programmed cell death ligand 1 (PD-L1), and cytotoxic T-lymphocyte-associated protein 4 (CTLA-4)) are currently used in clinical practice for the treatment of several cancers." (PMID 31847096, 2019). "Moreover, modern treatment-strategies for advanced cancer should focus on the rational delivery of systemic therapy and on the optimal combination strategies or sequence with novel agents such as cytotoxic T-lymphocyte-associated protein 4 (CTLA-4) inhibitors and other immunotherapy." (PMID 29545941, 2018). "Moreover, effective CTLA-4 and PD-1 blockade immunotherapy appears to be associated with the presence of T cells directed toward mutant cancer neoepitopes, and with the likelihood of MHC presentation of these neoantigens and subsequent recognition by specific T cells." (PMID 29403496, 2018). "Hence, our study aimed to assess whether a heterozygous germline mutation in CTLA4 is associated with a decreased risk to develop cancer." (PMID 30250467, 2018). "Thus, therapeutic stimulation of Axl functions in RA DCs to rebalance the immune system could bring clinical improvement in RA, similar to CTLA‐4 therapy, albeit with careful cancer risk factor monitoring." (PMID 29315512, 2018). "The development of cancer and chronic infections is facilitated by many subversion mechanisms, among which enhanced expression of immune checkpoints molecules, such as programmed death-1 (PD-1) and cytotoxic T lymphocyte-associated antigen 4 (CTLA-4), on exhausted T cells." (PMID 29023417, 2017). "Recently, cancer immunotherapies received a high degree of attention, which mainly contained the treatments for programmed death 1 (PD-1), programmed death ligand 1 (PD-1L), cytotoxic T lymphocytes-associated antigen 4 (CTLA-4) and chimaeric antigen receptors (CARs)." (PMID 28053197, 2017). "This hypothesis is supported, for instance, by the higher effectiveness of treatment with anti CTLA-4 therapeutic mAbs in cancers characterized by a high mutational load, likely to result in a higher expression of mutated proteins potentially recognized as “non-self” by the adaptive immune system." (PMID 28337438, 2017).